C3AR1 (complement C3a receptor 1)
Diseases named in the same sentence as C3AR1 in open-access papers (continued):
Sharing a sentence is not in itself a finding about the gene and the disease.
ovarian carcinoma (12 papers, 2019 to 2025). A malignant neoplasm originating from the surface ovarian epithelium. "C3AR1 overexpression significantly increased the proliferation of ovarian cancer SKOV3 cells and was associated with immunosuppression and poor prognosis of ovarian cancer." (PMID 38714753, 2024). "This study demonstrates that C3AR1 is up-regulated and promotes cancer cell proliferation in ovarian cancer, as well as associated with various pathological features." (PMID 37005667, 2023). "In summary, our study suggested that C3AR1 is associated with the prognosis and immune cell infiltration of ovarian cancer, and is a promising immunotherapeutic target." (PMID 37005667, 2023). "In particular, C3AR1 overexpression is associated with immune cell infiltration, mediating the tumor immune microenvironment, and is associated with poor prognosis of ovarian cancer patients." (PMID 37005667, 2023). "In vitro experiment indicates that increased C3AR1 promotes the proliferation of ovarian cancer cells." (PMID 37005667, 2023). "First, we compared the difference of C3AR1 between ovarian cancer and other human tumors and normal tissues." (PMID 37005667, 2023). "This study aims to determine role of C3AR1 in prognosis and regulating tumor infiltrating immune cells of ovarian cancer (OC)." (PMID 37005667, 2023). "Bioinformatics analysis (TCGA, CPTAC) and immunohistochemical staining of clinical samples confirmed higher C3AR1 expression in ovarian cancer than that in normal tissues." (PMID 37005667, 2023). "KEGG and GO analysis showed that the biological processes of C3AR1 in ovarian cancer are mainly involved in T cell activation, cytokine and chemokine activation." (PMID 37005667, 2023). "In ovarian cancer, the C3a anaphylatoxin chemotactic receptor (C3AR1) is associated with the activation of T cells and the penetration of immune cells by mediating m6A modification in OC cells, which results in the development of ovarian cancer." (PMID 39904996, 2025). "Therefore, we evaluated the correlation between C3AR1 and chemokines, interleukins and interferons in the ovarian cancer microenvironment in the TCGA database." (PMID 37005667, 2023). "Taken together, these results indicate that C3AR1 may be a potential new immunotherapeutic target for ovarian cancer." (PMID 37005667, 2023). "Immunohistochemistry verified the expression of C3AR1 in ovarian cancer and control tissues." (PMID 37005667, 2023). "However, the prognostic value of C3AR1 and its possible mechanism in ovarian cancer remains unclear." (PMID 37005667, 2023). "We speculate that the combined use of small molecule inhibitors targeting C3AR1 and ICB may be a promising strategy for the treatment of ovarian cancer." (PMID 37005667, 2023).
tauopathy (12 papers, 2019 to 2025). Neurodegenerative disorders involving deposition of abnormal tau protein isoforms (tau proteins) in neurons and glial cells in the brain. "Finally, C3AR1 has been implicated as a key player in the spread of tau neuropathology in mouse models, while the complement system more generally is thought to be a key regulator of neuronal loss in primary tauopathy as well as AD." (PMID 37464408, 2023). "C3ar1 inactivation attenuates Tau pathology by reversing deregulated immune networks in Tauopathy models and AD." (PMID 31959236, 2020). "However, given the importance of this gene and the complement pathway more generally in tauopathy and AD, analysis of peripheral C3AR1 expression in larger, better-powered cohorts is still warranted." (PMID 37464408, 2023). "Pathology in the PS19 tauopathy model is reduced when they are crossed with constitutively null C3aR1 mice but it is possible that C3aR1 deletion may have significantly different effects on amyloidosis." (PMID 31924226, 2020). "Finally, we examined the expression of C3AR1 given its importance in models of tauopathy." (PMID 37464408, 2023). "Notably, in a previous study, C3ar1 (C3a receptor) deletion rescued tau pathology and attenuated neuroinflammation, synaptic deficits, and neurodegeneration in the PS19 tauopathy mouse model." (PMID 37371067, 2023).
asthma (11 papers, 2005 to 2025). "This pooling-based GWAS in French Canadian adult women followed by lung eQTL mapping suggested C3AR1 as a functional locus associated with asthma." (PMID 27445529, 2016). "The same direction of effect is observed in the current study as the asthma risk allele increased the mRNA expression levels of C3AR1 in the three cohorts, which is also consistent with the study on circulating monocytes." (PMID 27445529, 2016). "The SNP was in perfect LD with the asthma-associated SNP rs17801353, which had a similar association with mRNA C3AR1 levels (P = 7.90E − 10)." (PMID 27445529, 2016). "A polymorphism in C3AR1 is associated with children with asthma who have manifestations of AD." (PMID 40309766, 2025). "In this study, one functional SNP located 7.6 kb from C3AR1 was associated with asthma." (PMID 27445529, 2016). "The most influential nodes (Fn1, Igf1, Ccl2, C3, Timp1, Cxcl12, Ccl4, Ccr2, Spp1, C3ar1, Cat, Cyp2e1, Muc5ac, Muc5b) were selected for further validation in the OVA-induced asthma and post-asthmatic fibrosis murine model." (PMID 35625754, 2022).
atherosclerosis (10 papers, 2011 to 2024). A disease characterized by the build-up of fatty material and calcium deposition in the arterial wall resulting in partial or complete occlusion of the arterial lumen. "Since C3aR1 has been previously associated with inflammation and atherosclerosis this might be one of the interesting candidates in our experiments to link both disorders." (PMID 21827714, 2011). "One studies have shown that after in vitro and in vivo injection of endotoxin and LPS, six candidate genes (BATF, BID, C3aR1, IL1RN, SEC61B and SLC43A3) were identified to be associated with inflammation and atherosclerosis." (PMID 36303246, 2022). "There are multiple lines of evidence for the role of C3aR1 in atherosclerosis." (PMID 21827714, 2011). "Interestingly, we observed that the immunoinflammatory biological processes and atherosclerosis deterioration-related pathways shared some common genes, including LYN, PTGIR, F11R, and C3AR1." (PMID 34095251, 2021).
ischemia (10 papers, 2012 to 2025). A hypoperfusion of the BLOOD through an organ or tissue caused by a PATHOLOGIC CONSTRICTION or obstruction of its BLOOD VESSELS, or an absence of BLOOD CIRCULATION. "Although C3-deficient mice develop limited ischemia and ischemia/reperfusion injury, we found that C3aR1-deficient mice develop ischemia and ischemia/reperfusion injury, as also noted by others." (PMID 28928734, 2017).
COVID-19 (9 papers, 2022 to 2025). A disease caused by infection with severe acute respiratory syndrome coronavirus 2. "In COVID-19 non-survivor genes related to neutrophil chemotaxis and migration, including CXCL10, CCL20, CCL8, C3AR1, CCL2, VAV3 are significantly upregulated; increased neutrophil is a typical signature of COVID-19 and closely linked to fatality, as already reported by other studies." (PMID 37949875, 2023).
pulmonary fibrosis (9 papers, 2017 to 2023). Chronic progressive interstitial lung disorder characterized by the replacement of the lung tissue by connective tissue, leading to progressive dyspnea, respiratory failure, or right heart failure. "Activated complement C3a was shown to stimulate human epithelial lung cells to express TGF-β1 and pharmacological blockade of C3ar1 attenuated the development of pulmonary fibrosis in bleomycin-treated mice." (PMID 35625754, 2022). "Inhibiting the expression of galectin-3 showed a stronger effect against the development of pulmonary fibrosis than inhibiting C3ar1." (PMID 33771973, 2021). "At the same time, we intraperitoneally injected the mice with the C3ar1 antagonist SB290157 or the galectin-3 antagonist GB1107 during the development of BLM-induced pulmonary fibrosis." (PMID 33771973, 2021). "Along the time axis of pulmonary fibrosis, the expression trends of C3ar1 and Lgals3 were highly consistent with the results of pseudo-temporal analysis." (PMID 33771973, 2021). "scRNA-seq revealed that genes complement C3a receptor 1 (C3ar1) and galectin-3, which play a key role in EC dynamic transition, were ubiquitously expressed by ECs in BLM-induced lung fibrosis, and ECM deposition was reduced and lung fibrosis was relieved after inhibition of this gene expression." (PMID 36825939, 2023).
Anxiety (7 papers, 2021 to 2025). Intense feelings of nervousness, tension, or panic often arise in response to interpersonal stresses. "Genetic deletion of the complement C3a anaphylatoxin chemotactic receptor (C3ar1), a key component of the innate immune response, is reported to induce behavioural phenotypes resembling anxiety and hyperactivity in mice, suggesting a neurodevelopmental role for this gene in health." (PMID 41306817, 2025). "Overall, these findings suggest that C3ar1 deficiency does not result in robust anxiety-like or hyperactive phenotypes, nor deficits in recognition memory or PPI." (PMID 41306817, 2025). "In Cohort 2, most anxiety-related and locomotion measures showed no genotype differences, except for reduced distance travelled in the centre of the OF arena by C3ar1-deficient mice (uncorrected two-sample t-test P < 0.01, Cohen's d = 0.92)." (PMID 41306817, 2025). "To rule out any potential confounding effects from co-housing littermate mutants and wild-types, we also examined whether the number of C3ar1-deficient cage-mates influenced wild-type behaviour but found no consistent pattern or evidence of systematic anxiety-like effects in wild-types." (PMID 41306817, 2025).
epilepsy (7 papers, 2021 to 2023). A brain disorder characterized by episodes of abnormally increased neuronal discharge resulting in transient episodes of sensory or motor neurological dysfunction, or psychic dysfunction. "The bioinformatics analysis results from the GSE36791 and GSE143272 datasets indicated that two genes—MMP9 and C3AR1—were strongly associated with SAH complicated with epilepsy." (PMID 36741285, 2023). "In the acute stage of ischemic stroke, increased levels of C3 signaling through C3aR1 are associated with worsening pathology and can lead to the development of epilepsy." (PMID 38035266, 2023). "The roles of MMP-9 and C3AR1 in the pathogenesis of epilepsy have been reported previously, but the mechanisms of the genes associated with SAH-induced epilepsy had not been studied." (PMID 36741285, 2023). "Finally, MMP9 and C3aR1 were identified as hub genes, and RT-PCR confirmed that the expression levels of the hub genes were higher in epilepsy and SAH samples than in normal samples." (PMID 36741285, 2023). "Focus on C3AR1 mediating tau pathology might represent a novel opportunity to research therapy for epilepsy." (PMID 34555062, 2021). "Thus, SAH may induce epilepsy through the regulation of pathogenic pathways by immune-related genes (IRGs), such as the expression levels of the MMP9 and C3AR1 genes in the immunoregulatory pathways leading to the occurrence of epilepsy." (PMID 36741285, 2023). "The results showed that the expression of MMP9 and C3AR1 was higher in SAH patients than in normal individuals and that the incidence of epilepsy in SAH patients with significant expression of these two IRGs was significantly higher." (PMID 36741285, 2023). "Neuroinflammation is closely related to the occurrence of epilepsy, which also indicates that increased MMP-9 and C3AR1 content may have a synergistic effect on the occurrence of epilepsy through inflammation." (PMID 36741285, 2023). "In summary, we identified the hub genes, namely, MMP9 and C3AR1, of SAH complicated with epilepsy and determined that they may work by regulating immune cell infiltration." (PMID 36741285, 2023).
osteosarcoma (7 papers, 2021 to 2024). A usually aggressive malignant bone-forming mesenchymal neoplasm, predominantly affecting adolescents and young adults. "Among them, C3AR1 mRNA was associated with prognosis, metastasis, and tumor immune microenvironment in osteosarcoma." (PMID 33748161, 2021). "Among them, C3AR1 mRNA was focused, which was associated with outcomes and metastasis in osteosarcoma." (PMID 33748161, 2021). "Collectively, C3AR1 expression may associate with tumor immune microenvironment in osteosarcoma." (PMID 33748161, 2021). "used integrative analysis of single-cell and bulk transcriptome data to discover neutrophil-related genes in osteosarcoma, such as C3AR1 and FCER1G." (PMID 39324133, 2024). "C3AR1 was down-regulated in osteosarcoma tissues and cells, and its overexpression inhibited the proliferation, migration, and invasion of osteosarcoma cells and induced apoptosis." (PMID 37744272, 2023). "We analyzed the correlation between C3AR1 expression and clinicopathological characteristics among osteosarcoma patients." (PMID 33748161, 2021). "Hence, C3AR1 mRNA may be linked with tumor immune microenvironment in osteosarcoma." (PMID 33748161, 2021). "Hence, C3AR1 mRNA could be an underlying therapeutic target for osteosarcoma." (PMID 33748161, 2021). "C3aR1 has been shown to be expressed abnormally in a variety of human cancers, and it predicts resistance to chemoradiation and poor prognosis in osteosarcoma." (PMID 34880862, 2021). "Our findings indicate that the mRNA expression of C3AR1 and FCER1G may serve as a predictive factor for the prognosis of osteosarcoma patients and is closely associated with metastatic progression." (PMID 39062086, 2024). "In osteosarcoma tumor microenvironment-related literature, we take notice that the connection between the score of immunity and survival state has been investigated, and C3AR1, PPARG, PDK1, IGHG3, and C1Q are recognized as prognostic biomarkers." (PMID 36844870, 2023). "C3AR1 was verified to be down-regulated in osteosarcoma tissues and cells." (PMID 33748161, 2021). "After overexpressing C3AR1, proliferation and apoptosis of osteosarcoma cells were evaluated." (PMID 33748161, 2021). "C3AR1 was further verified in osteosarcoma tissues and cells." (PMID 33748161, 2021). "After validation, C3AR1 was down-regulated in osteosarcoma tissues and cells." (PMID 33748161, 2021). "Taken together, our study identified a novel stromal- and immune-related C3AR1 mRNA, which could be tightly correlated to outcomes of osteosarcoma patients." (PMID 33748161, 2021). "Thus, lowly expressed C3AR1 mRNA could be correlated to poor prognosis and metastasis in osteosarcoma." (PMID 33748161, 2021). "Collectively, C3AR1 mRNA could be a prognostic marker for prognosis and metastasis in osteosarcoma." (PMID 33748161, 2021). "C3AR1 mRNA might be a feasible therapeutic target in osteosarcoma therapy." (PMID 33748161, 2021). "We found that C3AR1 mRNA could be a predictive factor for prognosis of osteosarcoma patients." (PMID 33748161, 2021). "In summary, C3AR1 and FCER1G mRNA hold potential as prognostic markers for both prognosis and metastasis in osteosarcoma." (PMID 39062086, 2024). "C3AR1 and FCER1G were highly regulated in the osteosarcoma mice induced by K7M2, and these two genes were proven to have significant prognostic value in osteosarcoma." (PMID 39582869, 2024). "Hence, C3AR1 mRNA might be a promising therapeutic target for osteosarcoma." (PMID 33748161, 2021). "C3AR1 expression was distinctly decreased in metastatic compared to non-metastatic osteosarcoma patients (p = 0.037)." (PMID 33748161, 2021). "There was a lower mRNA expression of C3AR1 in metastatic than non-metastatic osteosarcoma." (PMID 33748161, 2021).
osteosarcoma (continued). "There was a weak negative correlation between C3AR1 expression and T cells CD4 naïve levels in osteosarcoma samples." (PMID 33748161, 2021). "A weak negative correlation between C3AR1 expression and T cells CD4 naïve levels was found among osteosarcoma samples (r = −0.26; p = 0.0017)." (PMID 33748161, 2021).
cognitive decline (6 papers, 2018 to 2025). "Notably, the expression of C3 and C3aR1 positively correlates with cognitive decline and further increases with progression of disease in the hippocampus of PS19 mice." (PMID 40641620, 2025). "Furthermore, as the expression of complement C3 and C3aR1 in the human AD brain are correlated with cognitive decline, the inactivation of C3aR attenuates tau pathology, neuroinflammation, and neurodegeneration in mice models of AD." (PMID 37571393, 2023).
coronary artery disease (6 papers, 2019 to 2025). "In a study of GWAS among the Chinese population, variant 3′ UTR C3AR1 (rs7842 A/G) was identified in the eQTL analysis and was associated with C3AR1 expression levels and coronary heart disease." (PMID 35327350, 2022).
diabetic nephropathy (6 papers, 2021 to 2026). "Hub genes (FPR3, C3AR1, CD14, ITGB2, RAC2 and ITGAM) related to iron death in diabetic nephropathy were obtained through gene expression differential analysis between different subtypes." (PMID 34735495, 2021). "Finally six Hub genes related to iron death in diabetic nephropathy were obtained, including FPR3, C3AR1, CD14, ITGB2, RAC2 and ITGAM." (PMID 34735495, 2021).
glioma (6 papers, 2022 to 2025). A benign or malignant brain and spinal cord tumor that arises from glial cells (astrocytes, oligodendrocytes, ependymal cells). "Elevated expression of both C3 and its receptor C3AR1 has been associated with poor survival outcomes in patients with glioma, particularly in IDH-wild-type GBM." (PMID 40843669, 2025). "Complement component 3 (C3) and the receptor C3AR1 were both associated with aggressive disease and shorter survival in human glioma." (PMID 39172519, 2024). "Furthermore, C3AR1 was associated with shorter survival in glioma as well as in IDH-WT GBM." (PMID 39172519, 2024). "The C3a/C3AR1 axis is critically involved in promoting glioma cell self-renewal, as well as in the polarization of macrophages and microglia, and it has been implicated in facilitating leptomeningeal metastasis." (PMID 40843669, 2025). "Because of the high expression of C3AR1 in GBM, we tested the effect of the C3aR antagonist SB290157 in the extreme limiting dilution assay (ELDA) — a functional assay measuring the self-renewal capability of U3082MG glioma cells." (PMID 39172519, 2024). "C3AR1 increased with glioma grade and IDH-WT status and was expressed at higher levels in GBM as compared with nontumor brain." (PMID 39172519, 2024). "The q-PCR results showed that MSR1 (p < 0.05), IL18 (p < 0.05), SLC11A1 (p < 0.05), and C3AR1 (p < 0.05) were highly expressed in the glioma tissue compared with the normal tissues." (PMID 37370848, 2023). "The identification of the downstream signals of HK2 demonstrated that the high expression of hub genes, including ITGB2, CD53, C3AR1, CYBB and ITGAM, maybe a potential target for the treatment of glioma." (PMID 35982398, 2022).
Hypertension (5 papers, 2019 to 2025). The presence of chronic increased pressure in the systemic arterial system. "The protective effect of C3ar1 deficiency was then overcome by additional aging and ocular hypertensive injury." (PMID 33176797, 2020). "Nevertheless, despite local complement playing a role in arteriosclerosis, knockout of C3aR1, C5aR1, and C5aR2 in a hypertension mouse model had no apparent effect on hypertension and cardiac injury." (PMID 40519170, 2025).